CRP (C-reactive protein)
Diseases named in the same sentence as CRP in open-access papers (continued):
Sharing a sentence is not in itself a finding about the gene and the disease.
Sepsis (continued). "CRP (AUC 0.901) and procalcitonin (AUC 0.845) showed greater accuracy than presepsin (AUC 0.706) for diagnosing sepsis." (PMID 36832265, 2023). "C-reactive protein concentrations were higher in patients with sepsis and septic shock than in other patients." (PMID 37110181, 2023). "While IL-6, PIGF, and CRP were also significantly elevated in post-Sepsis patients compared to controls, the observed differences in TNFα, Tie-2, Flt-1, IL-7 and bFGF were unique to the post-COVID group." (PMID 36844209, 2023). "Constant monitorization of CRP levels is an effective tool in the detection of sepsis, showing a higher sensitivity compared to white blood cell count or body temperature measurement." (PMID 37371805, 2023). "More than 200 biomarkers of sepsis are described, such as C-reactive protein (CRP), procalcitonin, calprotectin, and some inflammatory cytokines, e.g., tumor necrosis factor (TNF)-α and interleukin (IL)-6, IL-8, IL-10, and IL-12." (PMID 38003758, 2023). "Two non-colonized patients in the low VAP suspicion group, with declining CRP levels on day 6 (91 and 24 mg/L), developed sepsis on day 12 of the study, which increased CRP levels to 278 mg/L." (PMID 37237823, 2023). "Out of the analyzed parameters, only SOFA score and serum concentrations of creatinine, PCT and CRP revealed significant changes within five days after ICU admission in sepsis." (PMID 36767629, 2023). "The table presents the results, and the IVW fixed-effects analyses showed a positive correlation between CRP levels and Sepsis and Sepsis (under 75)." (PMID 37662942, 2023). "To date, the sepsis biomarkers that commercially available in Japan are CRP, PCT, presepsin and IL-6." (PMID 37324133, 2023). "On the other hand, patients with viral coinfections had more frequent fever, higher C-reactive protein levels and developed sepsis in a greater proportion than those with a single infection." (PMID 37845714, 2023). "In humans and animals, CRP, which is a long-established marker of sepsis, is increased in patients with sepsis." (PMID 37048125, 2023). "CRP appeared to be a good classifier for Sepsis (compared with SIRS) at this and the Day2 time points." (PMID 38332914, 2023). "As expected, in terms of laboratory parameters, infants with sepsis presented more elevated levels of classic infection biomarkers such as CRP and procalcitonin (p < 0.001)." (PMID 37892278, 2023). "The premorbid ambulation ability with albumin and C-reactive protein can be combined to predict 28-day mortality in elderly patients with sepsis." (PMID 35962331, 2022). "A cross-sectional study was conducted to assess the prognostic predictability of PCT and CRP in neonatal surgical sepsis." (PMID 36158418, 2022). "For example, according to our data, CRP of > 1.5 mg/dL, obtained > 6 hours from symptoms onset, in an infant who weighs > 1000 g, has 100% sensitivity to diagnose sepsis." (PMID 36517750, 2022). "As with the discovery set, SOFA, CRP, and lactate values on admission were higher in sepsis than SIRS, while higher WBCs in sepsis on admission and close to the time of sampling were not statistically significant." (PMID 35844509, 2022). "PCT and IL-6 had lower AUC’s than CRP in predicting sepsis but their sensitivity was higher – 87% for PCT and 86% for IL-6." (PMID 35550043, 2022). "The results in our work confirm that IL‐6, IL‐8, d‐dimer, and CRP are primarily the best indicators of identifying patients with sepsis." (PMID 36176597, 2022). "Regarding inflammatory biomarkers, chemerin showed a significant positive correlation with CRP and procalcitonin only at sepsis onset." (PMID 35204801, 2022). "Several studies have shown that CRP is a good biomarker for diagnosing bacterial infection and sepsis." (PMID 35149284, 2022). "Circulating chemerin and CRP at sepsis onset outperformed procalcitonin, IL-6, IL-10 and suPAR in discriminating sepsis from septic shock." (PMID 35204801, 2022).
Sepsis (continued). "CRP and PCT have been largely studied as diagnostic markers in sepsis in both, children and adult populations, IL-6 have been studied in children and neonates." (PMID 35550043, 2022). "Despite some disadvantages, CRP concentration seems to be a useful biochemical post-mortem marker, especially in sepsis." (PMID 35215147, 2022). "In ROC curve analysis, d1 serum CK-18 fragment predicted severe sepsis with an area under the curve (AUC) of 0.767, CRP with an AUC of 0.764, and PCT with an AUC of 0.731." (PMID 34255216, 2022). "During a 3-day-stay at a local hospital, the patient’s symptoms rapidly deteriorated and sepsis screen reported a CRP of 153.04 mg/dl and Procalcitonin (PCT) of 16.44 ng/ml." (PMID 35401464, 2022). "sTREM-1 in serum and urine is more sensitive for the early diagnosis of sepsis than C-reactive protein (CRP) and procalcitonin (PCT)." (PMID 36209190, 2022). "CRP, nCD64 index were independent predictors of 28-day mortality for sepsis in the Cox regression model [CRP, HR 1.004 (95% CI 1.002–1.006), P < 0.001; nCD64 index, HR 1.263 (95% CI 1.187–1.345, P < 0.001]." (PMID 35907785, 2022). "Other studies have shown that children with FPIES present with normal or mild elevations in CRP when compared to elevated values seen in bacterial gastroenteritis or sepsis." (PMID 35769585, 2022). "C-reactive protein (CRP) is an established marker for systemic inflammation in dogs that is especially elevated in dogs with sepsis." (PMID 36713872, 2022). "A recent analysis showed that combining CRP with other biomarkers can increase sensitivity or specificity for Candida sepsis (AUC = 0.912)." (PMID 35330311, 2022). "A less commonly used sepsis biomarker is assessment by flow cytometry of the expression of CD64 on the surface of neutrophils (nCD64) in response to acute systemic inflammatory activation, which out-performs both the CRP and Pct in sepsis detection." (PMID 35176042, 2022). "It has been demonstrated that CRP has a lower sensitivity for sepsis diagnosis in preterm compared to term newborn, and that CRP rise induced by infection in preterm infants is significantly lower and with shorter duration." (PMID 36517750, 2022). "There are many causes for elevated CRP levels other than sepsis, including inflammation, burn injuries, cardiovascular disease, and malignancy, which all contribute to the low specificity and limited usage of CRP as a sepsis biomarker." (PMID 35054993, 2022). "Sepsis-associated immunosuppression will be associated with longer duration of antibiotics, due to persistently raised PCT and CRP; more hospital-acquired infection and more antibiotic treatment days." (PMID 36600326, 2022). "Clinical doctors’ preliminary judgment of sepsis is based primarily on inflammatory markers and etiological detection, such as blood culture, CRP, PCT, WBC, and other definitive tests." (PMID 36189371, 2022). "Clinical and laboratory parameters suchlike sick appearance, neutrophil–lymphocyte ratio > 1.5, and C-Reactive Protein > 0.75 were able to detect late-onset sepsis at the earliest." (PMID 34984642, 2022). "On each of these occasions, there was a concern for sepsis due to fevers > 38°C and a C-reactive protein (CRP) > 200 mg/L." (PMID 36654597, 2022). "Logisti univariate analysis showed that NLR level, CRP level, PCT, and APACHE II score were associated with 28 days mortality in patients with bloodstream infection and sepsis (P < 0.05)." (PMID 35345421, 2022). "Presepsin, procalcitonin (PCT), and C-reactive Protein (CRP) are the most used in clinical practice for sepsis diagnosis, although, in LC, the cut-off values are different compared to the general population." (PMID 36143057, 2022). "In the univariable Cox proportional hazards model, CRP, PCT, nCD64 index were associated with 28-day mortality of sepsis (P < 0.001)." (PMID 35907785, 2022). "This makes it superior to CRP in identifying bacterial infection and sepsis in surgical patients, particularly postoperative patients." (PMID 36475186, 2022).
Sepsis (continued). "ROC curve analysis revealed that the diagnostic value of plasma WBC, CRP, and TNF-α for sepsis was dissatisfactory, while PCT and IL-6 were slightly better." (PMID 36402943, 2022). "Fibrinogen, another essential inflammatory biomarker of acute-phase inflammation, is a key protein in the coagulation cascade and plays an important role in the prognosis of sepsis, similar to CRP." (PMID 35990041, 2022). "We found the median serum CRP was significantly higher in confirmed sepsis cases compared to probable sepsis, being 6 mg/L(IQR =3-18.3) in confirmed sepsis and 2.7 mg/L (IQR =2.1-7.7) in probable sepsis cases." (PMID 36467887, 2022). "The levels of CREA, PCT and CRP in sepsis groups were higher than those of the non-sepsis group, while the level of ALB was lower (p<0.05)." (PMID 36189371, 2022). "In this way, the C-reactive protein/lymphocyte ratio, C-reactive protein/leukocyte ratio, neutrophil/monocyte ratio, and neutrophil/lymphocyte ratio demonstrated their potential as prognostic biomarkers in patients with sepsis." (PMID 35601226, 2022). "Markers of systemic inflammation (CRP and procalcitonin) and stress (glucose) were significantly elevated in sepsis." (PMID 35204114, 2022). "In the sepsis group, the mean CRP level, WBC, PCT level, and PSEP level were 13.5 mg/dL, 14697.4 cu/mm, 2.6 ng/mL, and 863.3 pg/mL, respectively." (PMID 35666350, 2022). "Another study demonstrated that proadrenomedullin had the best predictive accuracy of 28-day mortality in patients with sepsis or septic shock in comparison with C-reactive protein, procalcitonin, and lactate." (PMID 36072940, 2022). "Our clinical validation with patient samples covers the whole dynamic range observed in sepsis patients, and our quantification successfully navigates the hook effect for CRP." (PMID 35149284, 2022). "Increased IL-6 levels can lead to an acute phase response (inducing expression of C-reactive protein and fibrinogen, thereby enhancing localized infection) and is correlated with the severity of sepsis." (PMID 36060742, 2022). "CRP is also used as a standard for measuring sepsis as part of the clinical standard, or blood culture." (PMID 36176597, 2022). "SAA-1 was more accurate in predicting early-onset sepsis than CRP (sensitivity (96 vs. 30%), specificity (95 vs. 98%)." (PMID 35329889, 2022). "The median total leucocyte count (TLC) and CRP were statistically higher in the sepsis group than the control group (13.70 versus 8.15 × 103/μl; p=.002 and 14.0 versus 4.0 mg/l; p ˂ .001)." (PMID 35770922, 2022). "C-reactive protein is an important prognostic marker and an early predictor of sepsis in patients with severe thermal burns." (PMID 35822791, 2022). "Subjects meeting the criteria of sepsis showed elevated CRP and leukocyte counts (p < 0.05, respectively)." (PMID 36551906, 2022). "Several biomarkers, such as procalcitonin, C-reactive protein, interleukin (IL)-6, and other inflammatory factors, have been proposed for sepsis detection." (PMID 35991069, 2022). "Hemodynamic parameters are often unstable in extreme inflammatory settings such as sepsis, which also present dramatically high circulating CRP levels with peaks of ≥150 mg/L CRP." (PMID 35207331, 2022). "It means that MDW is a useful screening indicator for sepsis in the patients with a suspected infection, and it is effective test to confirm sepsis along with CRP and PCT results." (PMID 36538555, 2022). "In recent years, some clinical studies have found that the levels of inflammatory factors such as calcitoninogen (PCT) and C-reactive protein (CRP) have high clinical value in the early diagnosis of sepsis and determination of the disease." (PMID 35345421, 2022). "One hundred sixty-five (86%) patients had at least 1 of the 4 indicators (CRP > 10, leukocyte count > 12, sepsis score ≥ 2, or bowel resection performed)." (PMID 35005586, 2022).
Sepsis (continued). "Markers of neutrophil extracellular traps formation (cfDNA) and NET degradation (nucleosome and DNase I) were significantly elevated in EONS; as well as CRP which is one of the possible laboratory signs of sepsis according to the EMA criteria." (PMID 35053308, 2022). "Chemokines have several benefits over CRP as a measure of newborn sepsis, including their quick rise in level (within two to four hours after infection)." (PMID 35449688, 2022). "Because the variables CRP, leukocyte count, and sepsis scores were dependent, they were examined individually, as were bowel resections." (PMID 35005586, 2022). "Corroborating with this, sepsis-related laboratory parameters such as CRP, thrombocytopenia, neutrophilia and lymphocytopenia also showed improved values in the PP group." (PMID 36376345, 2022). "CRP, combined with sFAS showed increased sensitivity in predicting sepsis than CRP alone, and CRP, PCT, IL-6, sFAS and sVCAM-1 combined had the highest AUC compared to other biomarker combination models." (PMID 35550043, 2022). "CRP performance was similar between infants who received antimicrobial therapy at the time of sepsis workup (N = 26; 6 with bacterial infections) and those who did not." (PMID 36517750, 2022). "The C-reactive protein (CRP)-to-albumin ratio (CAR) was initially developed as a prognostic factor for patients with sepsis." (PMID 36558435, 2022). "It has been reported that the treatment of mice with severe sepsis using a synthetic CRP molecule mitigates their liver injury and increases their survival rate." (PMID 35008905, 2022). "In patients with sepsis, the plasma concentration increases faster than CRP or PCT level, and when EIA is performed, PSEP can be detected within 4 h of infection." (PMID 35666350, 2022). "The advantage of using IL-6 as a sepsis marker is that its concentration rises quickly once bacteremia begins, even before CRP levels rise." (PMID 35449688, 2022). "ROC analyses of the biomarkers to predict sepsis showed that the areas under the curve were 0.742 (95% CI 0.662–0.822) for CRP, 0.696 (95% CI 0.615–0.778) for hsa-let-7d-3p, and 0.627 (95% CI 0.541–0.713) for the WBC count." (PMID 35907902, 2022). "C‐reactive protein (CRP) is an acute phase reactant that increases during periods of inflammation, e.g., due to sepsis or trauma." (PMID 36036654, 2022). "Possible differential diagnoses, considering the persistent positivity of the blood cultures and elevated CRP levels, were sepsis by a different pathogen or alternative foci of the infection (abscess, meningitis, pneumonia, or endocarditis)." (PMID 35455502, 2022). "Thrombocytopenia should be considered as the first sign of sepsis, even before the rise of infective markers such as CRP and raised TLC in neonates." (PMID 35386168, 2022). "Initially, among them, C-reactive protein (CRP), procalcitonin (PCT), interleukin-6 (IL-6), have been postulated as diagnostic and prognostic biomarkers in sepsis, although with limitation." (PMID 36459524, 2022). "When compared with other frequently used biomarkers, such as WBC and CRP, all markers performed poorly for the discrimination of sepsis versus non-sepsis patients." (PMID 35631080, 2022). "In our study, PCT and CRP levels were higher in the sepsis group than in the non-sepsis group, consistent with previous research." (PMID 36189371, 2022). "C-reactive protein and procalcitonin have been widely used in clinics for infection diagnosis and sepsis progression prediction." (PMID 35991069, 2022). "Serial CRP estimations for establishing or excluding the diagnosis of septicemia in neonates have existing evidence." (PMID 36246087, 2022). "An elevated CRP concentration at the time of sepsis workup predicted EOS and LOS with limited sensitivity but good specificity values in this study." (PMID 36233706, 2022).
Sepsis (continued). "In a pediatric study (n = 60/55 healthy and sepsis patients), miR-146a is decreased in blood and negatively correlated with the levels of C-reactive protein, procalcitonin (PCT), IL-6 and TNF." (PMID 35990654, 2022). "A cross sectional study was conducted to compare the performance of PCT, CRP, leukocyte count and lactate levels compared to blood culture in critically ill patients admitted with suspicion of sepsis." (PMID 36167572, 2022). "Procalcitonin and CRP are considered the most sensitive and effective biomarkers to assess the severity of bacterial co-infection or sepsis." (PMID 35677912, 2022). "An elevated CRP above 5.5 mg/L at the time of sepsis workup predicted CP EOS with a sensitivity of 80% and a specificity of 74%." (PMID 36233706, 2022). "No alterations of procalcitonin (PCT) and C-reactive protein (CRP) were detected excluding the diagnosis of sepsis." (PMID 35135591, 2022). "Pancreatic stone protein (PSP) is a novel biomarker that is more sensitive and specific to sepsis than CRP and PCT." (PMID 35867213, 2022). "A previous study reported that presepsin was superior to PCT and CRP in discriminating sepsis from SIRS in acute abdominal conditions." (PMID 34983420, 2022). "In a meta-analysis evaluating the use of procalcitonin and C-reactive protein in the sepsis diagnosis of adult patients, procalcitonin had an 85% specificity and 77% sensitivity, and C-reactive protein had an 80% specificity and 61% sensitivity." (PMID 35130306, 2022). "Two days after birth the patient became tachypneic, and sepsis work-up revealed an increased C-reactive protein (CRP) level of 21 mg/l (N < 10 mg/l) which rose suspicion of a perinatal infection." (PMID 35782614, 2022). "When compared to CRP, PCT's rapid rise with the onset of bacterial sepsis makes it a good diagnostic for infant sepsis early diagnosis." (PMID 35449688, 2022). "CPB time, 1.08 (1.02–1.14); high BMI (per 5 kg/m2), 1.58 (1.15–2.18); preoperative renal malperfusion, 9.06 (2.82–29.13); perioperative sepsis, 2.82 (1.19–6.66); perioperative peak C reactive protein, 1.06 (1.02–1.10)." (PMID 36036431, 2022). "Studies report a 5-20 fold rise from baseline in PCT values in comparison with a three to eight-fold rise in CRP values in the setting of sepsis." (PMID 36158418, 2022). "Performance of serial measurements and combination of CRP with earlier markers such as CD64, interleukins or procalcitonin have the potential to improve the diagnostic accuracy in the early phases of sepsis in both EOS and LOS." (PMID 35345614, 2022). "Compared to common inflammatory biomarkers such as CRP, procalcitonin or IL-6, HBP is unique in that it induces vascular leakage, and therefore microcirculatory dysfunction, the hallmark of sepsis-induced organ dysfunction." (PMID 36035420, 2022). "According to studies evaluating the diagnostic value of the existing diagnostic tests for sepsis, PCT has a higher diagnostic value than the traditional diagnostic tests, such as CRP, WBC, and interleukin (IL)-6." (PMID 35666350, 2022). "Complete blood count, CRP, procalcitonin, and renal function tests are also indicated in older unwell-appearing children requiring hospitalization to monitor sepsis and exclude renal failure." (PMID 36009990, 2022). "The prognostic value of presepsin was superior to that of PCT and CRP in patients with sepsis and septic shock." (PMID 34983420, 2022). "Numerous biomarkers for the diagnosis and detection of sepsis at an early stage have been identified, such as C-reactive protein (CRP), procalcitonin (PCT), and interleukins (ILs), but they have poor specificity." (PMID 34990478, 2022). "A recent study using Sepsis-3 reported that presepsin and PCT were superior to CRP and lactate in discriminating sepsis and septic shock from systemic inflammatory response syndrome (SIRS) without infection." (PMID 34983420, 2022). "The CAR has recently been considered as a more useful indicator of sepsis than CRP or albumin alone." (PMID 35887857, 2022).